TNF (tumor necrosis factor)
Diseases named in the same sentence as TNF in open-access papers (continued):
Sharing a sentence is not in itself a finding about the gene and the disease.
Arthritis (continued). "With the use of ST2 knockout mice and ST2 neutralizing antibodies in the CIA model, suppression of ST2 signaling alleviated arthritis symptoms and reduced levels of IL-17, TNF-α, and IFN-γ." (PMID 34589505, 2021). "IL-17 inhibition can alleviate arthritis in murine models of arthritis refractory to TNF inhibition." (PMID 34945224, 2021). "Bonifati and Graceffa reported 7 patients who experienced worsening or a flare of psoriatic arthritis after they were switched from TNF-α inhibitors to ustekinumab, suggesting that ustekinumab has better performance on skin symptoms than on joint inflammation." (PMID 34829740, 2021). "The main cytokines involved in the inflammatory cascade of arthritis are tumour necrosis factor-α (TNF-α), interleukin (IL)-6, and IL-1." (PMID 33478498, 2021). "With respect to the regulation of ACE and ACE2 production in arthritides, in animal models of arthritis, Ang1−7 exerted significant anti-inflammatory effects as it attenuated oxidative stress, as well as TNF-α, interleukin 1 (IL-1) and IL-6 production." (PMID 35155468, 2021). "The activities of proinflammatory cytokines interleukin 1 beta (IL-1β), IL-6 and tumor necrosis factor alpha (TNF-α) contribute to the pathogenesis of arthritis by promoting proteolytic enzyme activity that damages the cartilage extracellular matrix." (PMID 34198264, 2021). "PNS attenuates arthritis, improves LVs, and prevents TNF-induced LMC apoptosis by inhibiting NO production of LECs." (PMID 33602317, 2021). "As for arthritis symptoms assessment, we found that NG-R1 treatment group did significantly attenuate the degree of joint malformation and ankle circumference in TNF-Tg mice compared to the model group." (PMID 35280253, 2021). "Another preclinical study showed that intragastric administration of L. casei prevented the development of Salmonella enterocolitis-induced arthritis and reduced expression of proinflammatory cytokines (e.g., IL-1β, IL-6, IL-17, IL-23, and TNF-α)." (PMID 34065638, 2021). "Since TNF is an important pro‐inflammatory cytokine and plays a key role in pathogenesis of inflammatory arthritis, we investigated the role of TNF in arthritis induced by lupus serum IgG." (PMID 32994999, 2020). "The joint tissue TNF-α levels were increased by 35% in the arthritis group when compared to the control group." (PMID 32659877, 2020). "TNF-α inhibitors can significantly improve the clinical symptoms of human TNF transgenic (hTNFtg) mice with spontaneous arthritis, and they are frequently used in patients with severe RA." (PMID 32958016, 2020). "As a result, in experimental arthritis model, MG treatment decreases the levels of cytokines such as TNF-α, IL-6, and IL-17." (PMID 32659877, 2020). "Treatment with this preparation in a collagen II-induced arthritis mouse model demonstrated to reduce the pathological picture of arthritis, with decrease of TNF-α, IFN-γ, and Cox-2 especially in mice arthritic joints." (PMID 31979082, 2020). "Among the regulation factors, laccase domain-containing protein 1 (LACC1) regulates TNF and IL-17 in mouse models of arthritis and inflammation." (PMID 32350307, 2020). "By genetic approach, it was found that CatK deficiency largely prevented the cartilage erosion and bone destruction and reduced the joint inflammation in mice with TNF-α-mediated arthritis." (PMID 32582709, 2020). "In a type II collagen-induced arthritis rat model, MT exerted its anti-arthritis effects via down-regulation of pro-inflammatory cytokines and proteins (IL-6, IL-8, IL-1β, IL-17A, and TNF-α) and down-regulation of NF-κB." (PMID 33041782, 2020). "For example, the receptor tyrosine phosphatase sigma (PTPRS) activating decoy protein attenuated severity of arthritis when combined with low dose of a TNF inhibitor, but was insufficient in itself to have an effect." (PMID 33390996, 2020).
Arthritis (continued). "Further, systemic inflammation, like what occurs in arthritis and other chronic musculoskeletal pain, results in producing inflammatory cytokines, such as plasma interleukin 6 and tumor necrosis factor-alpha." (PMID 33066753, 2020). "In contrast to microglia, the response of astrocytes is poorly characterized in TNF-driven arthritis and only based on the expression of glial fibrillary acidic protein (Gfap)." (PMID 33362800, 2020). "TNF is a key pro-inflammatory cytokine among them as its overexpression is sufficient to induce arthritis in mice (hTNFtg)." (PMID 33396412, 2020). "Higher cardiovascular risk in patients with PsA can also be attributed to the combination of skin and joint inflammation, releasing higher amounts of pro-inflammatory cytokines, such as tumor necrosis factor (TNF)-α, interleukin (IL)-6, IL-17 and IL-23." (PMID 32028959, 2020). "During the progression of arthritis, for example, Atsttrin similarly exhibited its cartilage-protective effect through both inhibiting TNFα/TNFR1-mediated inflammation and activating anabolic TNFR2 pathways [reviewed in]." (PMID 33195216, 2020). "At the time of the survey, 30% of patients were on no immunosuppressive medications for their irAE, 41% were on corticosteroids and 12% were on a biological agent (TNF or IL-6R inhibitor) for arthritis." (PMID 33067320, 2020). "Conversely, the genetic deletion of Sphk2 showed minor effects on disease progression in the mouse model of TNF-α-induced arthritis, whereas the pharmacologic inhibition with the SPHK2 inhibitor ABC294640 augmented disease severity." (PMID 32630814, 2020). "The pharmacological study on madecassoside demonstrated that it can effectively lessen the related inflammatory factors in arthritis model rats (TNF-α ↓, IL-1b ↓, IL-6 ↓, IFN-γ ↓, IL-17 ↓)." (PMID 33013406, 2020). "Since SAE1/UBA2 function is predominately dependent on TNF-α–induced activation in vitro, we also determined the effect of GA on joint inflammation in TgTC mice, a human TNF-α transgenic model of arthritis." (PMID 32938830, 2020). "After administration, the levels of IL-6, IL-1β, and TNF-α decreased, and the arthritis detumescence percentages increased significantly, and the bony erosion degree was distinctly decreased in the TP-CMCS groups and TP group." (PMID 32110979, 2020). "TNF-α is widely present in the serum and arthritis synovium of RA patients, acting on a variety of cells in joint space, amplifying and cascading inflammatory process." (PMID 32477138, 2020). "The reduction in clinical arthritis score is within in the range of that observed for TNF and IL-1 blockade, but the comparison should be interpreted with caution as the severity of the CIA model is variable between experiments and laboratory environments." (PMID 32381123, 2020). "In contrast to TNF-driven arthritis, lymphoid cell-based models of RA like CIA or antigen-induced arthritis (AIA) were less extensively investigated regarding neuroinflammation, mainly focussing on the hippocampus and cortex." (PMID 33362800, 2020). "Previous studies have suggested that isorhamnetin attenuates collagen-induced arthritis via modulating the levels of cytokines TNF-α, IL-1β, and IL-6 etc. in the joint tissue homogenate of mice." (PMID 32754034, 2020). "Inflammatory mediators in arthritis, such as prostaglandin IL-1β, IL-6, and TNF-alpha, directly affect the lymphatic function and reduce the frequency of lymphatic pumps." (PMID 32280355, 2020). "During this process, cytokines, such as TNF and IL-6, also play a critical role in the pathogenesis of inflammation in arthritis." (PMID 32958016, 2020). "One is the most widely accepted, the CIA mouse model, and the other is the TNF-Tg mice model with TNF-α overexpression, both of which showed clear joint inflammation, similar to RA, before undergoing treatment." (PMID 32116720, 2020).
Arthritis (continued). "TNF-α can effectively reduce the arthritis and synovitis symptoms of RA patients, and RA can be suppressed by inhibiting the expression of TNF-α." (PMID 33062015, 2020). "The primary cytokines required for inducing arthritis in autoimmune models are IL-1β, IL-6, IL-17A, TNF, GM-CSF, and RANKL." (PMID 32792961, 2020). "The joint tissues TNF-α levels were decreased by 20% in the MG group when compared with the arthritis group (P ˂ 0.05)." (PMID 32659877, 2020). "On the other hand, serum TNF-α, IL-6, and IL-17 levels were lower (36%, 29%, and 41%, respectively) in the MG group when compared with the arthritis group (P < 0.001 for all three)." (PMID 32659877, 2020). "NET formation and arthritis in the murine TNFα-induced inflammatory arthritis were investigated to identify the roles of PAD2 and PAD4 for citrullination." (PMID 33584645, 2020). "Cytokines that are produced locally in the joint during arthritis, like IL-1, TNFα, IL-6, and IL-17, have been shown to modulate neurons." (PMID 32854769, 2020). "In contrast, in arthritis and some other conditions, IL-33 serves as a pro-inflammatory cytokine and exacerbates inflammation and pain via promoting the production of TNF-α, CXCL1, IL-1β and PGE2 through ST2 in plantar skin tissues 37-39." (PMID 33204337, 2020). "Deposition of IgG, monocytes/macrophages and TNF‐α is all required for the development of arthritis." (PMID 32994999, 2020). "Behavioral analyses are needed to answer the question if TNF-driven arthritis overall ameliorates or worsens AD-like phenotypes in 5XFAD mice." (PMID 33362800, 2020). "In contrast, TNFR2 expression was restricted to non-neuronal cells of the macrophage-monocyte lineage that increased dependent on TNF during experimental arthritis." (PMID 32528961, 2020). "We also determined the pathological function of BAD in TNF-Tg mice, another murine model of experimental arthritis in which overexpression of human TNFα leads to inflammatory-erosive arthritis." (PMID 33270017, 2020). "Serum IL-6, TNF-α, and IL-17 levels were higher in the arthritis group than the control group (P ˂ 0.001 for all three)." (PMID 32659877, 2020). "To this end, we perform here a detailed analysis and characterization of the transmembrane TNF overexpressing TgA86 transgenic mouse model, which has been previously shown to develop arthritis, and we show that it reproduces main features of human SpA." (PMID 33023659, 2020). "Overall, our study demonstrates that [18F]fluoride is not an appropriate tracer to quantify the extent of local inflammation‐mediated bone damage and remodeling processes in joints from this TNF‐driven arthritis model." (PMID 31063606, 2019). "In summary, by applying a combination of high-dimensionality technologies, we have identified functional perturbations of the immunome in patients with arthritis who will relapse on withdrawal for anti-TNFα therapy." (PMID 31540934, 2019). "With this study we address the need for such comparisons at the mechanistic/molecular level by using an established arthritis model widely used for the preclinical evaluation of anti-TNF therapeutics." (PMID 31071076, 2019). "Considering these facts, it is then logical to attribute the reduced CFB levels observed in the CSF of our arthritis patients to the reduced TNFα levels induced by the infliximab treatment." (PMID 30770760, 2019). "By contrast, local administration of PlGF-2123-144-α-TNF suppressed arthritis development almost completely in the treated paw even at a 1000× lower dose." (PMID 31870429, 2019). "After the induction of arthritis in mice, TNF-α and MCP-1 levels increased significantly while IL-10 levels decreased significantly in the synovial tissues of the CIA group, compared to the healthy control group." (PMID 31382595, 2019). "IBD patients with arthritis/arthralgia or sacroiliitis/ankylosing spondylitis were more often treated with anti-TNF and patients with arthritis/arthralgia underwent more often IBD-related surgeries." (PMID 31039159, 2019).
Arthritis (continued). "Anti-TNF, but not anti-IL1, treatment significantly reduced the synovitis severity compared to the severity in the PBS-treated controls, indicating that Lpl1-induced arthritis is partially mediated by TNF-α." (PMID 31226163, 2019). "Several immune-related proteins in the CSF of arthritis patients decreased during TNF blockade, including FGG and CFB that both correlated strongly with systemic inflammation." (PMID 30770760, 2019). "Among these pathologic cytokines, IL-17 and TNF-α are assumed to be direct inductors of arthritis, enthesitis, and gut inflammation." (PMID 30630513, 2019). "On the other hand, anti-TNF antibodies are commonly used for treating arthritis and arthritis/arthralgia in IBD patients." (PMID 31039159, 2019). "Tumour necrosis factor alpha (TNFα) has been linked to pain mechanisms as well as cognitive dysfunction, and TNF-blocking treatment, e.g. infliximab, is described to ameliorate pain as well as fatigue in arthritis patients." (PMID 30770760, 2019). "TNF is one of the key mediator of arthritis or arthritis-like diseases in humans by triggering severe inflammation." (PMID 31031770, 2019). "Various inflammatory mediators are responsible for arthritis and articular deformity, such as TNF-α, IL-6, and IL-17." (PMID 31772500, 2019). "Cationic liposomes containing DMAPAP lipid have been successfully used previously to deliver siRNA to silence TNF-α in experimental arthritis and Receptor Activator of Nuclear factor Kappa-B (RANK) in a polyethylene particle-induced osteolysis model." (PMID 30669699, 2019). "Our results showed that the onset and the progression of TNF-mediated arthritis is dramatically affected by deregulated RANKL expression, supporting an underestimated role of RANKL in inflammatory osteolytic diseases." (PMID 30804932, 2019). "An “arthritis proteome” identified that TNF blockade with infliximab decreased 35 proteins in the CSF." (PMID 31554244, 2019). "Mechanism studies have confirmed that A2AR activation attenuates progression of experimental arthritis by inhibiting TNF-α and IL-1β production, both of which are the key pro-inflammatory cytokines in the pathogenesis of inflammation flare." (PMID 30679935, 2019). "Only animals treated with the TNF inhibitor showed clinical improvement on the arthritis signs and symptoms." (PMID 31780864, 2019). "In a previous study, we reported that EA prevented arthritis from causing bone erosion by activing A2AR and by inhibiting TNF-α." (PMID 30956681, 2019). "The percent composition of various infiltrated populations showed a clear prevalence of granulocytes in TNF-driven arthritis upon RANKL overexpression." (PMID 30804932, 2019). "In particular, administration of a TRPV1 agonist inhibits TNF production in a rat model of arthritis." (PMID 30761069, 2019). "This is an intriguing fact since FGG was also found to be decreased in arthritis plasma following TNF blockade (etanercept) confirming the reasonability of our observation." (PMID 30770760, 2019). "We therefore investigated the effects of TNF blockade on the arthritis CSF proteome and how candidate proteins related to clinical measures of disease activity and inflammation." (PMID 30770760, 2019). "Abundance of RANKL in TNF-driven arthritis worsens arthritis severity as shown by an increase in bone resorption, inflammatory cells and protein biomarkers indicative of extented osteoclastogenesis, tissue damage and activation of the immune system." (PMID 30804932, 2019). "Here, we investigated the effect of TNF inhibition alone on spinal progression when used during arthritis development in a murine model." (PMID 31784598, 2019). "SM significantly alleviated arthritis symptoms, inhibited bone erosion, and decreased the levels of TNF-α, IL-1β, CRP, ATX, and LPA in the sera of CIA rats." (PMID 31001354, 2019).
Arthritis (continued). "It was found that compared with the pre-arthritis phase, in which cytokine production increases sharply, it is easier to get efficacy from anti-TNF-α antibodies in the established phase, during which cytokine quantities are stable." (PMID 31618828, 2019). "The presence of TNF in peripheral and central structures is fundamental for joint pain in arthritis." (PMID 32038637, 2019). "We conclude that in vivo multimodal [18F]FDG μPET/CT imaging allows to quantify and monitor inflammation‐mediated bone damage and reveals not only reversal of synovitis but also bone repair upon TNF blockade in experimental arthritis." (PMID 31063606, 2019). "Like Enbrel, MTX also efficiently reduced the progression and severity of arthritis, presumably by reducing the levels of pro-inflammatory mediators such as IL-1, IL-6, TNF and prostaglandins." (PMID 30665457, 2019). "HDAC6 inhibitor, CKD-L decreased the arthritis score in collagen-induced arthritis model and reduced the expression of TNF-α and IL-1β in rheumatoid arthritis patients." (PMID 30841513, 2019). "In collagen II-induced murine arthritis and spontaneous arthritis in Hes1-GFP/TNF-transgenic mice, inhibited M1 polarization and simultaneously enhanced M2 polarization of Mφ significantly reduced the inflammatory response in the knee joints." (PMID 31178867, 2019). "After treated with enrofloxacin, significant alteration in cytokine expressions were detected, including higher levels of IFN-γ and IL-17A in arthritis model mice and higher TNF-α, IL-1β levels in chicken models." (PMID 31069173, 2019). "TNF, a pro-nociceptive cytokine, is directly involved in various pain disorders, including joint pain in different forms of arthritis, due to central and peripheral actions." (PMID 32038637, 2019). "Here, we show that TNF regulates the expression of the transcription factor interferon regulatory factor 1 (IRF1) in human FLSs as well as in a TNF transgenic arthritis mouse model." (PMID 31285419, 2019). "Antibiotics, steroids, immunomodulators, anti-TNF and calcineurin inhibitors were significantly more often used in patients with arthritis/arthralgia." (PMID 31039159, 2019). "Proteins selected (n = 27) give the highest contribution to the potential difference between arthritis CSF samples before and after TNF blockade." (PMID 30770760, 2019). "Intrathecal or systemic injection of etanercept, an agent clinically utilized for TNF neutralization, at day 7 post arthritis induction, alleviated the persistent joint hyperalgesia by specific action in DRG." (PMID 32038637, 2019). "Overall, these data support a relationship between arthritis symptoms and CNS inflammatory pathways as targets of the TNF inhibition." (PMID 31554244, 2019). "In contrast, the expression levels of the endogenous TNF and those of the human TNF transgene were similar between Tg197 and Tg197/Tg5519 mice, excluding their possible involvement in arthritis aggravation upon RANKL overexpression." (PMID 30804932, 2019). "Our results support that RANKL synergizes with TNF not only in local and systemic bone resorption but also in the inflammatory phenotype developed in modeled arthritis." (PMID 30804932, 2019). "TNF-α is a key pro-inflammatory cytokine contributing to RA-FLSs surviving and developing arthritis." (PMID 31396207, 2019). "In the present study, TNF also played an important role in Lpp-induced arthritis since a) Lpps induced TNF release in both macrophages and splenocytes and b) TNF inhibition, but not IL-1 inhibition, significantly reduced synovitis severity." (PMID 31226163, 2019). "Following a similar approach, the effect of RANKL overexpression in arthritis progression was studied in Tg197/TgRANKL double transgenic mice that simultaneously overexpress TNF and RANKL." (PMID 30804932, 2019). "The key role of TNF-α in chronic inflammatory disease is evidenced by potent anti-inflammatory effects of TNF-α antagonist on arthritis and age related sarcopenia." (PMID 31660942, 2019).